CHGA (chromogranin A)
Diseases named in the same sentence as CHGA in open-access papers (continued):
Sharing a sentence is not in itself a finding about the gene and the disease.
tumor (continued). "We investigated the tumor-homing properties of a chromogranin A-derived peptide containing an RGDL motif followed by a chemically stapled alpha-helix (called “5a”), which selectively recognizes the LAP/TGFβ complex-binding site of αvβ6 and αvβ8." (PMID 36594095, 2023). "The demonstration of the neuroendocrine nature of the tumor requires the identification of one or more neuroendocrine markers (synaptophysin, chromogranin A, CD56, or INSM1) in at least 10% of tumor cells." (PMID 36836564, 2023). "Histological examinations of the resected specimen from the both sites showed the same findings, as a high nucleus-to-cytoplasm ratio in the tumor cells, as well as immunohistochemically positive findings for chromogranin A, synaptophysin, and AFP." (PMID 37721573, 2023). "Immunohistochemical findings showed the tumor cells were positive for chromogranin A, synaptophysin, and CD56." (PMID 37031336, 2023). "Then, the loss of CHGA and UCHL1 increases susceptibility to oxidative stress and inhibits tumour aggression during clinical treatment." (PMID 37246623, 2023). "Further, a thorough laboratory follow-up including markers like NT-proBNP, 5-HIAA and chromogranin A, evaluation of clinical symptoms including abdominal pain, diarrhea, flush, and tumor load is necessary to evaluate disease status and progression." (PMID 37055717, 2023). "In terms of immunophenotype, the tumor tissues express chromogranin A (CgA), synaptophysin (Syn), and CD56." (PMID 37724114, 2023). "Chromogranin A had been used as a valuable tumor marker in NETs and elevated levels of CgA and 5-HIAA as well, has previously been associated with poor prognosis was associated with poor outcome." (PMID 38317712, 2023). "Immunohistochemical analysis also revealed the presence of a more intense staining for chromogranin A in tumor samples from the hyponatremic group." (PMID 38069002, 2023). "In fact, MTV and chromogranin A represent the imaging-based and laboratory estimates of tumor burden, respectively." (PMID 37359009, 2023). "For disease follow-up, ENETS recommends that tumor markers including chromogranin A, NT-proBNP and 5-HIAA need to be evaluated on a regular basis, annually or semi-annually, depending on the respective levels." (PMID 37055717, 2023). "Immunohistochemical investigations revealed that tumor cells were positive for chromogranin A, synaptophysin, and CD56." (PMID 37031336, 2023). "Tumor size, Ki-67 index, and location in the head were prognostic factors for disease recurrence, while age, plasma chromogranin A, and proliferation predicted mortality in patients with unresectable disease or residual tumors after resection." (PMID 38201527, 2023). "She then underwent spleen-preserving distal pancreatectomy; a 10-mm tumor positive for chromogranin A, synaptophysin and insulin was identified." (PMID 37563593, 2023). "Immunohistochemistry revealed that the tumor cells diffusely and strongly expressed cytokeratin, synaptophysin, chromogranin A, GATA3, CAM5.2, and estrogen and progesterone receptors; partially expressed AR and GCDFP15." (PMID 38115331, 2023). "First, we analyzed the levels of serotonin and chromogranin A in Patient 1’s tumor-draining and peripheral vein samples." (PMID 37007151, 2023). "The following variables did not correlate with recurrent disease: age, gender, mitotic count, chromogranin A level, size of the tumor, and resection approach." (PMID 36979807, 2023). "One example is chromogranin A, a protein found in secretory vesicles, which is a very reliable marker in tumour sections but was rarely detected in cell cultures." (PMID 36178902, 2022). "Immunohistochemically, the tumor cells were positive for synaptophysin, chromogranin A, and calretinin and were focally positive for NeuN, TTF1, NF, CK8, vimentin, and S100 proteins." (PMID 35663322, 2022).
tumor (continued). "On immunohistochemical staining, the tumor and supporting cells were positive for chromogranin A and the S 100 protein, respectively, and were diagnosed as PGL." (PMID 36090947, 2022). "The pleomorphic component was diverse and prominent atypical tumor cells proliferated, focally positive for chromogranin A, diffusely positive for synaptophysin, and the Ki-67 index was 67.1%." (PMID 35596001, 2022). "This high-grade tumour features a variable expression of neuroendocrine differentiation markers, including CD56, chromogranin A, synaptophysin and insulinoma-associated protein 1 INSM1." (PMID 35805976, 2022). "Circulating tumor cells (CTCs), the tumor cells in the peripheral blood, may be useful biomarkers for providing diagnostic and prognostic information, their presence is associated with higher tumor grade, tumor burden, an increased circulating chromogranin A concentration and higher Ki67 index." (PMID 36012893, 2022). "Chromogranin A (CgA) has been accepted as the most commonly used general tumor marker for the diagnosis, follow-up, and treatment monitoring of NEN patients, especially with non-functional tumors." (PMID 35205773, 2022). "Immunohistochemically, the tumor was positive for chromogranin A, CD56, and synaptophysin, and a diagnosis of paraganglioma of the urinary bladder was confirmed." (PMID 35676716, 2022). "Plasma tumor markers such as chromogranin A and neuro‐specific enolase are elevated in some advanced pulmonary NECs, but their role in gastroenteropancreatic NEC and gallbladder NEC is not clear." (PMID 34841738, 2022). "Immunofluorescence experiments showed that pPDH+ tumor cells were also ChgA+ and Ki67−, indicating that these transformed cells most likely derived from pPDH+ cells originally present in the normal intestine." (PMID 35314684, 2022). "A positive result for chromogranin A should be combined with the data on PTH expression in the removed tissues/nodule because other chromogranin A positive tumours enter the differential diagnosis." (PMID 35805976, 2022). "Apart from Chromogranin A, specific biomarkers predicting residual tumor disease, tumor burden, and disease progression in NEN are scant." (PMID 35205773, 2022). "Chromogranin A is a glycoprotein synthesized and stored in the neuroendocrine cells and can be used as a tumor marker in NETs reflecting tumor burden." (PMID 34110489, 2022). "The sheet-like component consisted of homogenous tumor cells, with chromogranin A and synaptophysin diffusely positive, and a Ki-67 index of 72.8%." (PMID 35596001, 2022). "Diffuse and intense cytoplasmic expression of synaptophysin and chromogranin A and nuclear staining for insulinoma-associated 1 (INSM1) reveals the tumor’s neuroendocrine differentiation, the common denominator of NENs." (PMID 34647171, 2022). "Immunohistochemical staining of the tumors showed that the positive rates of chromogranin A (CgA) and synaptophysin (Syn) were 21/23 and 13/13, respectively, which showed varying numbers of brown granules in the cytoplasm of tumor cells." (PMID 35558392, 2022). "Chromogranin A (CgA), Synaptophysin and neuron-specific enolase (NSE) are widely used in clinical routines as diagnostic tumor markers." (PMID 35326628, 2022). "Immunohistochemically, the tumor exhibited diffuse positivity for the expression of chromogranin A and synaptophysin and negativity for the expression of CD56." (PMID 34727269, 2021). "Immunohistochemically, the tumor exhibited diffuse positivity for the expression of chromogranin A and synaptophysin and focal positivity for the expression of CD56." (PMID 34727269, 2021). "Immunohistochemically, the tumor cells were positive for synaptophysin, chromogranin A, and CD56, indicating neuroendocrine differentiation." (PMID 33388069, 2021). "Immunohistochemically, the tumor was positive for chromogranin A, synaptophysin, and CD 56, and the Ki-67 index was 40%." (PMID 34727269, 2021).
tumor (continued). "We demonstrated that a high De Ritis ratio and high levels of the tumor marker Chromogranin A (CgA) each improved the prediction of the progression-free survival after treatment." (PMID 33562643, 2021). "Immunohistochemical analysis showed that the tumor cells are strongly positive for cytokeratin (AE1/AE3) and insulinoma-associated protein 1 (INSM-1), and scatteredly positive for chromogranin A, synaptophysin, and CD56, supporting the diagnosis." (PMID 34477164, 2021). "The neuroendocrine origin of the tumor spheroids was confirmed by immunoblotting analysis of neuroendocrine biomarkers: chromogranin A (CgA), somatostatin receptor 2 (SSTR2), and synaptophysin (SYP)." (PMID 34065268, 2021). "The most common tumour studies for diagnosis were chromogranin A and synaptophysin; serum chromogranin A and urinary 5-HIAA were also used frequently." (PMID 34109562, 2021). "These GEP-NET PDCOs maintained proliferation rates similar to the original tumor along with synaptophysin and chromogranin A expression that is characteristic of neuroendocrine cells." (PMID 33919802, 2021). "The baseline covariates included in the first model were as follows: treatment received, PD at baseline, previous therapy, sex, BMI, hepatic tumor load, primary tumor type, tumor grade, chromogranin A levels, DM, metformin use, and insulin use." (PMID 35008233, 2021). "In the present case, both the primary tumor and liver metastasis showed well-differentiated morphology and expressed typical neuroendocrine markers (chromogranin A and SSTR2), which indicated the liver metastasis to be well-differentiated NET-G3." (PMID 33742297, 2021). "An analysis comparable to our work assessed chromogranin A (CgA) regarding recurrence after panNEN surgery, combining CgA (>5× upper normal limit) with tumor size (≥4 cm) and G2/G3 grading to design a preoperative risk score." (PMID 32423000, 2020). "Among these, COL17A1, ITGB6, LAMC2, and S100P were upregulated in tumor tissues, whereas only CHGA was downregulated." (PMID 33015155, 2020). "At present, the only clinically available tumor marker, Chromogranin A (CgA), has been demonstrated to be of limited sensitivity and specificity and is in most cases only used to monitor tumor response to chemotherapy." (PMID 32486367, 2020). "Some series have shown that elevated chromogranin A levels can be observed months to years before the evidence of radiographic recurrence, suggesting its usefulness for the early detection of tumor relapse after successful curative resection." (PMID 32708330, 2020). "Circulating CHGA has been reported to correlate with tumor progression, presence of metastases, tumor burden and response to treatment in NENs, including PanNENs." (PMID 32537434, 2020). "Immunohistochemistry (IHC) staining for chromogranin A and synaptophysin, both of which are neuroendocrine markers, was diffusely and strongly positive in the tumor cells." (PMID 33031286, 2020). "All 163 tumours were immunoreactive for synaptophysin, 107 (66%) for chromogranin A and the median Ki67-index was 90% (range: 21–100%)." (PMID 31924180, 2020). "Immunohistochemical staining revealed that the tumor expressed chromogranin A, NSE and synaptophysin." (PMID 32569235, 2020). "In accordance with previous reports, CHGA can exert antiangiogenic effects and inhibit tumor growth in vivo." (PMID 32260415, 2020). "Plasma interleukin-6, thrombopoietin, and serum chromogranin A and -B were measured; furthermore, tumor tissue was immunohistochemically stained for CgA+." (PMID 33383764, 2020). "The literature states that various tumor markers—including neuron-specific enolase (NSE) and chromogranin A (CgA)—have been evaluated as sources for detecting NETs and as indicators of tumor development and response to therapy." (PMID 32563832, 2020). "By immunohistochemistry, the tumor cells were seen positive for Chromogranin A, Synaptophysin, CD56, INSM1, OSCAR, somatostatin receptor type 2 (SSR2), P16 and focally for ISLET1." (PMID 32854635, 2020).
tumor (continued). "Histopathologcal examination of the resected tumor confirmed the diagnosis of PGL with positive chromogranin A and synaptophysin stains and a Ki67 proliferation index of 3%." (PMID 31666924, 2019). "Pathological analysis revealed tumor cells positive for chromogranin A, synaptophysin and for S-100." (PMID 31689630, 2019). "Immunohistochemically, the tumor cells were positive for chromogranin A, synaptophysin, CD56, and TTF-1 and the Ki-67 index was 27%." (PMID 31511024, 2019). "CHGA is found in secretory vesicles of neurons and endocrine cells, but also widely expressed among NB tumours." (PMID 31638925, 2019). "Immunohistochemically, the tumor cells were positive for neuroendocrine markers (chromogranin A, synaptophysin, CD56) and thyroid transcription factor-1 (TTF-1)." (PMID 31511024, 2019). "In neuroendocrine gastro-intestinal cancers the plasmatic levels of chromogranin A are augmented in more than 80% of affected patients thus, is considered the main marker for this tumor type." (PMID 31263455, 2019). "Immunohistochemistry showed epithelial membrane antigen positivity, anti-pancytokeratin 1 markers of tumor cells positivity, chromogranin A negativity, actin negativity, S100 negativity, estrogen receptor negativity, and progesterone receptor negativity." (PMID 31151475, 2019). "Chromogranin A also exert a prognostic value, especially in general midgut carcinoids cases, because of the existing correlation with the tumor load." (PMID 31263455, 2019). "Results from IHC staining of the NE markers (SYP and ChgA) in tumor tissues of Enz-treated mice also indicated that Enz significantly increased the NED." (PMID 31189930, 2019). "Morphological analysis of tumour xenografts showed neuroendocrine differentiation with strong immunohistochemical staining for synaptophysin, chromogranin A, serotonin and pan-cytokeratin." (PMID 30730850, 2019). "Tumors deriving from A99 and TCC-NECT-2 were diffusely positive for chromogranin A and synaptophysin, and tumor deriving from TYUC-1 was focally positive for both of them." (PMID 29765522, 2018). "Immunohistochemically, tumor cells showed positivity for chromogranin A and synaptophysin; Ki-67 index was < 1.0%." (PMID 30037336, 2018). "All tumours ought to be examined for endocrine differentiation by immunohistochemistry with antibodies towards general NE markers like chromogranin A and synaptophysin." (PMID 30567376, 2018). "Spheres from tumor 26 were positive for chromogranin A (CgA) and TTF-1 expression, reflecting the SCLC/neuroendocrine phenotype of their tumor of origin." (PMID 29503225, 2018). "The tumours were also stained positively with other neuroendocrine markers, e.g., chromogranin A (39 positive/42 tested) and synaptophysin (32/35)." (PMID 30425741, 2018). "Immunostaining revealed that the tumor cells were positive for chromogranin A, synaptophysin, and CD56." (PMID 29218566, 2018). "Several metrics have been used in monitoring tumor response, among which chromogranin A (CgA) is currently recognized as the most valuable serum tumor marker used for screening, diagnosis, treatment, monitoring of progress, and prognostic evaluation." (PMID 30510495, 2018). "The tumor architecture is the most important diagnostic feature for MANEC, which is then confirmed by immunohistochemical findings such as chromogranin A, synaptophysin, CD56, and neuron-specific enolase expression." (PMID 29740725, 2018). "Immunohistochemically, tumor cells showed the expression of chromogranin A and synaptophysin, and a Ki-67 index < 1.0%." (PMID 30037336, 2018). "We followed up on this observation, assessing the extent of neuroendocrine differentiation in the patient's tumor by assessing the expression of synaptophysin and chromogranin A using IHC assays commonly implemented in the anatomic pathology laboratory." (PMID 28835367, 2017).
tumor (continued). "Immunohistochemical staining of metastatic gastric tumour was positive for both trypsin and chromogranin A in more than 40% of the tumour." (PMID 28357816, 2017). "The tumour was positive for adrenocorticotropic hormone, chromogranin A (CGA), and steroidogenic factor-1 (SF-1) on the tumour surface." (PMID 28193212, 2017). "The tumor stained positively with several neuroendocrine markers including chromogranin A, synaptophysin and somatostatin receptor-2." (PMID 28378747, 2017). "All tumor tissues were immunoreactive for either one or both neuroendocrine biomarkers (chromogranin A and synaptophysin) and Ki67 index was >20% in all cases." (PMID 29112960, 2017). "All tumors maintained diffuse strong nuclear MYCN expression, and cytoplasmic labeling for markers used to characterize human NBL (TH, TRKB, and Chromogranin A) was generally focal to multifocal in small to moderate numbers of tumor cells." (PMID 29238067, 2017). "Most of the tumour was positive for trypsin, an acinar cell marker (more than 90% of the tumour), and many cells were positive for chromogranin A, an endocrine marker (40–50% of the tumour)." (PMID 28357816, 2017). "Although tumor markers are used to help diagnosis and predict some types of cancers, chromogranin A, a widely used tumor marker of pNETs, has significant limitations." (PMID 29290942, 2017). "Chromogranin A (CgA) is currently used as a tumor marker for pNETs in western populations; however, its value is influenced by various factors including comorbid conditions or medications and lack of assay standardization." (PMID 29290942, 2017). "Immunohistochemical staining for the NE markers chromogranin A and synaptophysin showed strong staining of the tumor cells." (PMID 28097640, 2017). "Levels of NE cancer markers, which include aschaete-scute homolog 1 (ASCL1), synaptophysin (SYN), and chromogranin A (CgA), correlates with tumor burden." (PMID 29050323, 2017). "The median size of the tumours was 1.5 cm (range: 0.1–16.5 cm), of which 87.3 % (n = 110) and 98.4 % (n = 124) were positive for chromogranin A (CgA) and synaptophysin respectively." (PMID 26911576, 2016). "Tumor cells were positive for synaptophysin (reactivity rate 100%) and chromogranin A (reactivity rate 50%)." (PMID 27840759, 2016). "Staining of Brachyury within the tumour is broad and heterogeneous with occasional cells that are dual stained for both Brachyury (strongly stained cells) and ChgA." (PMID 26862851, 2016). "At diagnosis, the serum level of tumor marker chromogranin A was elevated at 1080 ng/ml (normal range <100 ng/ml), and the urinary 5-hydroxyindoleacetic acid (5-HIAA) was 29 mg/24 h (normal range 2 – 9 mg/24 h)." (PMID 27519265, 2016). "Immunohistochemically, tumor cells usually show positive reactivity for neuroendocrine markers, including synaptophysin and chromogranin A. In addition, these tumors generally show positive reactivity for ER and PgR." (PMID 28105053, 2016). "In contrast to the majority of these tumours, this biopsy was immunohistochemically positive for chromogranin A, and synaptophysin and Ki-67 index was 50% and the tumour was diagnosed as poorly differentiated neuroendocrine carcinoma of the oesophagus." (PMID 26955490, 2016). "For the other tumor markers (synaptophysin, chromogranin-A, NCAM, CK5/6, K903, p40, and p63), immunohistochemical expression did not correlate significantly with location of the primary tumors." (PMID 26705222, 2015). "To ensure that our xenograft models retained typical features of their respective subtype, we assessed expression of molecular markers specific to PCa (AR, PSA) and NEPC (SYP, CHGA) in the investigated Living Tumor Lab (LTL) tumor lines." (PMID 25859291, 2015). "Immunohistochemically, the tumor cells stained positive for synaptophysin and chromogranin A, which is consistent with human panPETs." (PMID 26192435, 2015).